PIK3CA (phosphatidylinositol-4,5-bisphosphate 3-kinase catalytic subunit alpha)
Diseases named in the same sentence as PIK3CA in open-access papers (continued):
Sharing a sentence is not in itself a finding about the gene and the disease.
mantle cell lymphoma (8 papers, 2014 to 2023). Mantle cell lymphoma is a rare form of malignant non-Hodgkin lymphoma affecting B lymphocytes in the lymph nodes in a region called the ``mantle zone''. "Mantle cell lymphomas (MCL) were shown to lack PIK3CA mutations, but often display constitutive AKT activation, resulting from loss of PTEN expression in some cases." (PMID 25096023, 2014). "Through gene expression profiling, several genes in mantle cell lymphoma cells have been identified that relate to the PI3K/Akt pathway; the following genes were found to be altered or upregulated: PIK3CA, PDK2, PDPK1, AKT1, RPS6KB2, FOXO3A, PPP2R2C, and PDK1." (PMID 29907126, 2018). "Gene amplification of PIK3CA has been considered to contribute to the pathogenesis of DLBCL and mantle cell lymphoma." (PMID 29029507, 2017). "Psyrri A and colleagues detected the genetic change of PIK3CA gene in mantel cell lymphoma using quantitative real-time PCR together with FISH method, showing that amplification of PIK3CA was frequent in both mantle cell lymphoma tissues (15/22, 68%) as well as its derived cell lines." (PMID 29029507, 2017).
medulloblastoma (8 papers, 2006 to 2023). A malignant, invasive embryonal neoplasm arising from the cerebellum. "For instance, the recommendation for a medulloblastoma patient with an activating PIK3CA mutation responding well to standard chemotherapy and radiation would be to continue SOC rather than receive a new, specific targeted therapy." (PMID 28423702, 2017). "In medulloblastoma, the PIK3CA gene is targeted by mutations at a low frequency, but the p110α isoform is also over-expressed in primary tumors and cell lines." (PMID 25915540, 2015). "Mutations in PIK3CA were reported in primary medulloblastoma, as well as increased expression of PIK3CA at the mRNA and protein level." (PMID 25915540, 2015). "The observation that LIFRα expression was elevated in the SHH subgroup of primary medulloblastoma, further supports this model, in view of the over-expression of PIK3CA in this subtype." (PMID 25915540, 2015). "Together, these data indicate a correlation between PIK3CA expression and GLI1 in medulloblastoma and raise the possibility of a functional relationship between PI3Kα signalling and the GLI1 transcription factor in HH driven cancers." (PMID 31492956, 2019). "Compared to GBM, the genetic alteration of PIK3CA (2%) and PIK3R1 (0.3%) in medulloblastoma (MBM), which is the most aggressive malignant brain tumor that highly occurs in children and survival rate can reach 70% after active treatment, are less frequently observed." (PMID 32333246, 2020). "This hypothesis was also confirmed by the observation that PIK3CA was over-expressed in primary medulloblastoma, compared to normal cerebellum, which was not the case for PIK3CB or PIK3CD." (PMID 25915540, 2015).
renal carcinoma (8 papers, 2008 to 2024). A carcinoma arising from the epithelium of the renal parenchyma or the renal pelvis. "This is in agreement with recent evidence that PIK3CA is upregulated by hypoxia in renal carcinoma cell lines." (PMID 18335034, 2008). "Interestingly, PIK3CA has been identified as a direct target of miR-490-5p and miR-19a in renal carcinoma." (PMID 31443717, 2019).
renal cell carcinoma (8 papers, 2015 to 2022). "A mutation in the helical domain of PIK3CA (p.E542K), which is known to be constitutively activating and selectively sensitive to everolimus, was found in a renal cell carcinoma patient with the PFS of 23.9 months." (PMID 26859683, 2016). "In this study, activating PIK3CA mutations in helical domain (p.E542K), and kinase domain (p.H1047R) were found in a renal cell carcinoma and a parotid gland choriocarcinoma patient, respectively." (PMID 26859683, 2016). "PPI networks were also analyzed for the genes involved in the ‘Renal cell carcinoma pathway,’ and several hub genes, such as PIK3CA, VEGFA, and PIK3CB were noted." (PMID 31443717, 2019). "The most related pathway to SOX2OT inhibition was renal cell carcinoma (Kegg: 05211, corrected p value = 0.004953) with 5 genes differentially expressed in RNA sequences of both cells (hif1a, hras, pik3ca, rap1b, vhl)." (PMID 30202240, 2018). "As for the regulated targets in the renal cell carcinoma pathway, TGFB1, EPAS1, HIF1A, VEGFA, KRAS, and PIK3CA regulated by miR-140 have been reported to interfere with KIRC." (PMID 35528546, 2022). "Hub genes in the ‘Renal cell carcinoma pathway’ based on PPI analysis, such as PIK3CA, VEGFA, and PIK3CB, were noted and have also been observed to play vital roles in ccRCC." (PMID 31443717, 2019).
urothelial carcinoma (8 papers, 2016 to 2026). A malignant neoplasm derived from the transitional epithelium of the urinary tract (urinary bladder, ureter, urethra, or renal pelvis). "Urothelial carcinomas with the APOBEC-high signature harbor also pathogenic PIK3CA mutations at the hotspot helical domain amino-acid positions E542 and E545, which may underline the tolerance of these cancers to high TMB." (PMID 35323317, 2022). "Many urothelial carcinomas (UC) contain activating PIK3CA mutations." (PMID 27465249, 2016). "Notably, both BC models with elevated COX-2 expression in metastases had PIK3CA driver mutations, suggesting a possible therapeutic benefit of COX-2 inhibition in PI3K-altered urothelial carcinoma." (PMID 40605119, 2025). "Potentially actionable genomic alterations included FGFR2/3, ERBB2, and PIK3CA, and alteration frequencies of these genes in resected MIBC from IMvigor010 were similar to the prevalence in advanced-stage urothelial carcinoma based on the FoundationCORETM dataset." (PMID 37601688, 2023). "PIK3CA is a protein in the nonpapillary urothelial carcinoma-specific PPI network." (PMID 41342186, 2025).
uterine endometrioid carcinoma (8 papers, 2015 to 2025). "The results showed that both PIK3CA mutations and PIK3R1 mutations were associated with endometrial endometrioid adenocarcinoma (EEA), compared with serous endometrioid adenocarcinoma (SEA) (OR = 1.9, 5.2 and p = 0.03, 0.00)." (PMID 37340596, 2023). "The results showed that LCK metagene expression is related to the prognosis of patients with endometrioid endometrial adenocarcinoma subtypes and highly correlated with the PTEN and PIK3CA mutational status." (PMID 33159014, 2020). "Alterations were seen in PTEN (71%) and PIK3CA (60%) of uterine endometrioid carcinoma." (PMID 36010253, 2022).
vulvar carcinoma (8 papers, 2014 to 2025). "In HPV 16-, 18-, 31-, and 33-positive vulvar carcinoma cases, a mutation rate of 73 % was observed, and mutations mainly occurred in genes involved in proliferation, differentiation, and apoptosis (PIK3CA, FGFR3, and PTEN)." (PMID 39170128, 2024). "We, therefore, searched for the PIK3CA mutation in relation to nearby cervical and vulva cancers." (PMID 40647429, 2025). "For instance, dactolisib, a dual anti-PIK3CA/mTOR inhibitor, exhibited promising antitumor efficacy in an in vitro model for vulvar cancer by counteracting epithelial-to-mesenchymal transition." (PMID 38397025, 2024). "The significance of PIK3CA, FGFR3 and FBXW7 mutations for vulvar carcinogenesis and vulvar cancer patient management remains to elucidated." (PMID 32664330, 2020). "In the present study, 25 vulvar carcinomas (of which 19 HPV-negative tumours) were analysed, and one PIK3CA, 3 CDKN2A, and 2 HRAS mutations were detected in the HPV-negative carcinomas." (PMID 24671188, 2014).
anal carcinoma (7 papers, 2013 to 2024). "In the present study we set out to verify the incidence of KRAS, BRAF and PIK3CA mutations in a series of patients with anal carcinoma and analysed the association between these alterations and the clinical-pathological characteristics of patients." (PMID 24642661, 2014). "Activating mutations in PIK3CA have been reported to arise in 20–25% of human anal cancers, suggesting that this pathway may be a relevant target for therapeutic interventions in the future." (PMID 38673429, 2024). "Our study shows that KRAS and BRAF are not mutated in anal carcinoma, whereas PIK3CA, mutated in about 20% of cases, may represent a mechanism of resistance to anti-EGFR treatment, such as cetuximab." (PMID 24642661, 2014). "Additionally, the importance of Akt activation is also observed in both anal cancer and HNSCC, although the issue of whether such a driver oncogenic pathway is caused by mutation of PIK3CA, loss of PTEN, HPV oncoproteins, or increased pro-inflammatory cytokines is still unknown." (PMID 24124460, 2013). "However, the incidence of other gene alterations, e.g. BRAF and PIK3CA mutations, involved in the response to anti-EGFR therapies in colorectal cancer has not been studied in anal carcinoma." (PMID 24642661, 2014).
anaplastic cancer (7 papers, 2014 to 2025). "TERT promoter, PTEN, and PIK3CA gene mutations are rare in adult DTC, while they have been found more frequently in poorly-differentiated carcinomas and anaplastic carcinoma." (PMID 31456750, 2019).
autism (7 papers, 2012 to 2025). Persistent deficits in social interaction and communication and interaction as well as a markedly restricted repertoire of activity and interest as well as repetitive patterns of behavior. "In lineage 3, PIK3CA, a risk gene for both autism and developmental delay, peaked in the middle part of the lineage." (PMID 39363111, 2024). "Of interest, the consensus for the Testing Eligibility Criteria for Somatic PIK3CA Mutations notes that macrodactyly combined with genitourinary, gastrointestinal, and neurologic abnormalities (including autism and hypoglycemia) should prompt respective testing." (PMID 40126231, 2025). "PIK3CA functions as a catalytic subunit of the mTOR pathway and has previously been found to be associated with developmental delay and DM, including one individual diagnosed with autism." (PMID 39887636, 2025). "Interestingly, one of these genes has previously been associated with both autism and DM individually, PIK3CA." (PMID 39887636, 2025). "Further, our cell-based data is consistent with the recent addition of PPP2R5D to the list of autism susceptibility genes related to AKT3, PIK3CA, PTEN, TSC1/2, and mTOR." (PMID 33482199, 2021). "A more comprehensive evaluation of the oncogene and tumor suppressor variants found in this study is ongoing; nevertheless, the variations discovered in two oncogenes, PIK3CA and MET, implicate specific mechanisms that could link autism and neoplasm." (PMID 26934580, 2016). "Probands from two of these families carried a second rare variant in addition to the HOMER1 variant, but these other variants did not co-segregate with the autism phenotype (HOMER1 c.290C>T and SHANK3 c.898C>T; HOMER1 c.195 and PIK3CA c.2294+19C>T)." (PMID 22558107, 2012).
breast adenocarcinoma (7 papers, 2015 to 2025). "Activating PIK3CA mutations were found in 20% of tumors, which has significant implications in advanced breast adenocarcinoma." (PMID 39191445, 2024). "We found that the initial breast adenocarcinoma was positive for a heterozygous mutation in PIK3CA (c." (PMID 25671134, 2015).
chordoma (7 papers, 2016 to 2025). Chordomas are rare malignant tumors arising from embryonic remnants of the notochord in axial skeleton. "Our genomic data confirmed previous findings that PIK3CA and chromatin remodeling genes were among the most frequently mutated genes in chordoma, while the potential driver role of LYST and USP9X were less certain." (PMID 39135136, 2024). "Other key mutations of dedifferentiated chordoma from the meta-analysis include CDKN2A/B, IRF2, KIT, PIK3CA, PTEN, RB1, and the TERT promoter." (PMID 38892063, 2024).
chronic lymphocytic leukemia (7 papers, 2017 to 2025). "Idelalisib, is an FDA-approved PIK3CA inhibitor for the treatment of patients with follicular lymphoma and small lymphocytic lymphoma." (PMID 32101536, 2020). "Chronic lymphocytic leukemia (CLL) patients rarely have PIK3CA mutations and amplification of PIK3CA has been reported in 5.6% of the cases." (PMID 32033478, 2020). "PIK3CA, which encodes the p100α catalytic subunit of PI3K, is the target of several PI3K inhibitors used to treat breast cancer (alpelisib), follicular lymphoma (copanlisib), and chronic lymphocytic leukemia (idelalisib)." (PMID 41342186, 2025).
depression (7 papers, 2014 to 2025). "PIK3CA, which is abundant in the nervous system, has been analyzed as a metabolite target of proteins in potential anti-depression medicine." (PMID 34095115, 2021). "The PIK3CA/AKT1 pathway is a core component in the pathogenesis of depression." (PMID 33935736, 2021). "Notably, hub genes such as Nrf2, AKT1, and PIK3CA are involved in key processes critical for neuronal survival, synaptic plasticity, and mood regulation, indicating their potential role in both the onset and progression of depressive disorders." (PMID 40290092, 2025). "Overall, our study verified that during states of excessive oxidative stress, the PIK3CA/AKT1/NFE2L2/KEAP1 and PIK3CA/AKT1/BDNF/NTRK2 signaling pathways are suppressed, which induced OB rats to exhibit phenotypic behaviors of depression." (PMID 33935736, 2021). "Moreover, the binding of NTRK2 and BDNF activates the PIK3CA/AKT1 pathway, which promotes synaptic plasticity and enhances long-term potentiation to alleviate depression." (PMID 33935736, 2021).
Focal cortical dysplasia (7 papers, 2015 to 2025). A type of malformation of cortical development that primarily affects areas of neocortex. "PIK3CA mutations affecting the mTOR–MAPK gene network cluster have been associated with focal cortical dysplasia and DRE and other epileptogenic brain lesions." (PMID 40103938, 2025). "Focal cortical dysplasias (FCDs) are localized MCDs, formerly believed to mostly result from a toxic insult to the developing brain, but recently also associated with DEPDC5 mutations and somatic mutations in MTOR, PIK3CA, AKT3, PTEN, TSC1 and TSC2." (PMID 35323703, 2022).
Hydrocephalus (7 papers, 2015 to 2025). Hydrocephalus is an active distension of the ventricular system of the brain resulting from inadequate passage of CSF from its point of production within the cerebral ventricles to its point of absorption into the systemic circulation. "PIK3CA-related hydrocephalus is a subtype of developmental hydrocephalus, caused by disrupted brain development associated with genetic abnormalities." (PMID 31094678, 2019). "So far, only mouse models with MCAP have been established, when activating PIK3CA mutations were introduced and accurately recapitulated several key human symptoms such as enlarged brain, cortical malformation, hydrocephalus, and epilepsy." (PMID 29549527, 2018). "A conditional Pik3ca knock-in transgenic mouse model induced at embryonic day (E0.5), displayed progressive hydrocephalus, ventriculomegaly, and megalencephaly, leading to death before weaning." (PMID 40386392, 2025). "Our data readily explain the coincidence of impaired neurogenesis, gyrification and hydrocephalus, observed often in patients with cortical dysplasia and in our Pik3ca mouse model." (PMID 31094678, 2019). "Both PIK3CA and PTEN genes connected with the PI3K–AKT–mTOR pathway are correlated with the pathogenesis of hydrocephalus through the mechanisms of cerebellar overgrowth and obstruction of CSF flow." (PMID 35047005, 2021).
Insulin resistance (7 papers, 2013 to 2024). Increased resistance towards insulin, that is, diminished effectiveness of insulin in reducing blood glucose levels. "PIK3R1, PIK3R2, and PIK3CA, encoding the p110α catalytic subunit, were next sequenced in 262 further probands with severe insulin resistance." (PMID 27766312, 2016). "PIK3CA-KCNMB3 variants are associated with insulin resistance in populations of different ancestries, and are modified by dietary PUFA." (PMID 23826284, 2013). "Putting together these data leads to the hypothesis that a single molecular impairment in the pathway of insulin signaling, including an incomplete interaction between PIK3CA(OMIM association number, 171834) and IRS1, may lead to insulin resistance, as well as insulin secretion defect." (PMID 30884193, 2019).